PROCA1 (protein interacting with cyclin A1)
Synonyms: MGC39650
Tractability: No criterion of Open Targets' tractability assessment is met for any kind of drug.
Gene: Protein-coding gene on chromosome 17 (28,703,197 to 28,711,888, reverse strand). Ensembl gene ENSG00000167525.
Subcellular location (Human Protein Atlas): Nuclear membrane; Golgi apparatus
Gene Ontology:
Molecular function: cyclin binding; phospholipase A2 activity
Biological process: arachidonate secretion; phospholipid metabolic process
Genetic constraint (gnomAD): Loss-of-function variants: 25 observed, 29.82 expected, observed/expected ratio (o/e) 0.84, 90% interval 0.61 to 1.17. The upper end of that interval is the gene's LOEUF score, 1.17, which puts it in group 5 of 6, group 1 being the genes least tolerant of losing a copy. Missense variants: 469 observed, 468.94 expected, observed/expected ratio (o/e) 1, 90% interval 0.93 to 1.08. Synonymous variants: 182 observed, 184.51 expected, observed/expected ratio (o/e) 0.99, 90% interval 0.87 to 1.12.
Homologues: Orthologues: chimpanzee PROCA1 (98% identical), macaque PROCA1 (95% identical), pig PROCA1 (72% identical), dog PROCA1 (70% identical), guinea pig PROCA1 (66% identical), rabbit PROCA1 (66% identical), rat Proca1 (49% identical), mouse Proca1 (45% identical), zebrafish proca1 (21% identical), tropical clawed frog proca1 (19% identical), zebrafish pla2g3 (16% identical), Drosophila melanogaster GIIIspla2 (8% identical), and 3 more. Paralogues in human: PLA2G3 (15% identical).
Diseases named in the same sentence as PROCA1 in open-access papers:
PROCA1 is named in the same sentence as 4 diseases in open-access papers, as found by Europe PMC text mining. Sharing a sentence is not in itself a finding about the gene and the disease. The quoted sentences say what the papers report.
cystic kidney disease (1 paper, 2012). A congenital or acquired kidney disorder characterized by the presence of renal cysts. "Analyses indicated 13 genes, in addition to Nek8 and Ift20 within this area that could potentially result in cystic kidney disease, namely: RGD1309077Phf12, Flot2, Spag5, Sdf2, Supt6h, Proca1, Traf4, Sarm1, Nlk and Ksr1." (PMID 22899815, 2012).
tumor (4 papers, 2011 to 2024). "PROCA1 played a potential tumor-suppressive role inducing cell apoptosis and DDP chemosensitivity via recruiting ZFP36L2 to bind to the 3′ untranslated region of BCL2, reducing the stability of BCL2 mRNA and thus activating the apoptotic signal." (PMID 36627670, 2023). "ProCA1.GRPR is distributed in regions encompassing the entire tumor, and the agent clearly penetrates the tumor vessels as shown by CD31 staining." (PMID 26577829, 2015). "In addition to relatively higher distribution in PC3 tumor tissue, ProCA1.GRPR was also largely distributed in liver and kidney." (PMID 26577829, 2015). "We have shown that contrast agents with a targeting peptide grafted in the loop region of ProCA1 have qualitatively better in vitro targeting abilities than those in which it is fused to the C-terminal of ProCA1 for GRPR expressed by both PC3 and DU145 tumor cells." (PMID 26577829, 2015). "By comparison, injection of ProCA1 without the GRPR targeting moiety or use of the clinical contrast agent Gd-DTPA to the tumor bearing mice did not result in any significant MRI contrast enhancement in tumor regions under the same conditions." (PMID 26577829, 2015). "It was clear that high levels of ProCA1-affi-m were targeted to the SKOV-3 tumor at 24 hours post injection, and the protein was distributed in the entire tumor evenly since its intensity is not changed significantly upon increasing the distance from vessel staining CD31 to 40 μm." (PMID 21455310, 2011).
PROCA1 also shares sentences with these, for which no sentence is quoted: cancer (2 papers); lung adenocarcinoma (1).